SOX11 (SRY-box transcription factor 11)
Diseases named in the same sentence as SOX11 in open-access papers (continued):
Sharing a sentence is not in itself a finding about the gene and the disease.
nasopharyngeal carcinoma (4 papers, 2013 to 2022). A carcinoma arising from the nasopharyngeal epithelium. "The findings shows that weak expression of SOX11 is related to methylation of SOX11 gene promoter in the tissues of nasopharyngeal carcinoma, and SOX11 re-expression is associated with demethylation of SOX11 gene by 5-aza-2'-deoxycytidine treated in CNE2 cells." (PMID 24188789, 2013). "Strong expression of SOX11 mRNA was detected in the nasopharyngeal carcinoma tissues of SOX11 gene promoter unmethylation and chronic inflammation tissues of pharynx nasalis." (PMID 24188789, 2013). "In a word,additional studies are required to elucidate which is the functional role of the illegitimate SOX11 expression in nasopharyngeal carcinoma." (PMID 24188789, 2013). "In this study, the expression and methylation status of SOX11 gene was detected in nasopharyngeal carcinoma and chronic inflammation tissues of pharynx nasalis." (PMID 24188789, 2013). "The effect of promoter methylation of SOX11 on growth and invasion of nasopharyngeal carcinoma cells was detected with MTT test and Boyden chamber Matrigel invasion assay." (PMID 24188789, 2013). "Strong expression of SOX11 protein was showed in the nasopharyngeal carcinoma tissues with SOX11 gene promoter unmethylation and chronic inflammation tissues of pharynx nasalis." (PMID 24188789, 2013). "In conclusion, the data provides a comprehensive characterization of the epigenetic mechanisms about SOX11 deregulation in nasopharyngeal carcinoma." (PMID 24188789, 2013). "We found that weak expression of SOX11 correlate with methylation of SOX11 gene in nasopharyngeal carcinoma tissues." (PMID 24188789, 2013). "In this study,methylation-specific PCR and real time quantitative PCR have been applied to investigate the effect of promoter methylation of the SOX11 gene on SOX11 expression in the nasopharyngeal carcinoma and chronic inflammation tissues." (PMID 24188789, 2013). "Strong expression of SOX11 gene was found in chronic inflammation tissues of pharynx nasalis and some nasopharyngeal carcinoma tissues with DNA unmethylation." (PMID 24188789, 2013). "Weak expression of SOX11 protein was detected in the nasopharyngeal carcinoma tissues with SOX11 gene promoter methylation." (PMID 24188789, 2013). "Strong expression of SOX11 mRNA was found in the nasopharyngeal carcinoma tissues with SOX11 gene promoter unmethylation and chronic inflammation tissues of pharynx nasalis." (PMID 24188789, 2013). "In this study, the effects of promoter methylation of the SOX11 gene on SOX11 expression and cell growth and invasion of nasopharyngeal carcinoma were investigated." (PMID 24188789, 2013). "SOX11 gene methylation may be plays a role in growth and invasion of nasopharyngeal carcinoma cells." (PMID 24188789, 2013). "SOX11 gene promoter methylation was found in 29 of 43 (67.4%) nasopharyngeal carcinoma tissues." (PMID 24188789, 2013). "Therefore, SOX11 gene methylation may play a role in growth and invasion of nasopharyngeal carcinoma cells." (PMID 24188789, 2013). "In the present study, we have performed on methylation of SOX11 gene, inclouding DNA methylation in the tissues of nasopharyngeal carcinoma and DNA demethylation in the CNE2 cell line (human nasopharyngeal carcinoma cell line)." (PMID 24188789, 2013). "No or weak expression of SOX11 mRNA was detected in the nasopharyngeal carcinoma tissues of SOX11 gene promoter methylation." (PMID 24188789, 2013). "No or weak expression of SOX11 gene was detected in some nasopharyngeal carcinoma tissues with DNA methylation." (PMID 24188789, 2013). "No expression or very weak expression of SOX11 mRNA was detected in the nasopharyngeal carcinoma tissues with SOX11 gene promoter methylation." (PMID 24188789, 2013). "Moreover, the presence of SOX11 promoter methylation has been shown to be significantly higher in patients with lymph node metastasis compared to patients without metastasis in nasopharyngeal carcinoma." (PMID 25880212, 2015).
Obesity (4 papers, 2017 to 2025). Accumulation of substantial excess body fat. "The lowest SOX11 mRNA expression level was found in overweight patients, and the highest in those with class I obesity." (PMID 40004707, 2025). "In addition, higher SOX11 mRNA expression levels were noted in the synovium of OA patients with class I obesity compared those who were overweight; however, its expression level was lower than that noted in patients with class II +III obesity." (PMID 40004707, 2025). "Finally, SOX11 mRNA expression level was the highest in overweight patients, but lowest in those with class I obesity." (PMID 40004707, 2025). "Our study revealed only SOX5 mRNA expression level in OA-affected articular cartilage with subchondral bone was positively correlated with BMI; however, we noticed SOX9 and SOX11 mRNA expression level was higher in patients with class II + III obesity compared to patients with class I obesity." (PMID 40004707, 2025). "In another study, a GWAS conducted on 1996 adult CCS (median age at diagnosis, 7.2 years; median age at follow-up, 32.4 years) identified potential obesity-associated loci on chromosomes 13 (FAM155A), 2 (SOX11), 4 (GLRA3), and 5 (CDH18, BASP1), particularly among CRT-exposed survivors." (PMID 41228239, 2025).
osteoporosis (4 papers, 2017 to 2024). A condition of reduced bone mass, with decreased cortical thickness and a decrease in the number and size of the trabeculae of cancellous bone (but normal chemical composition), resulting in increased fracture incidence. "miR-204-5p-SOX11 axis was proposed to have a role in ageing osteoblasts through downstream regulation of BMPR1A/Runx2 signalling involved in osteoporosis." (PMID 36614288, 2023). "In our study, we proposed the role of miR-204-5p-SOX11 regulation in aging osteoblasts, and the potential downstream regulation of BMPR1A/Runx2 signaling by SOX11, a signaling pathway involved in osteoporosis and OA." (PMID 29371932, 2017). "The SOX4, SOX11 and SOX12 (SOXC) transcription factors were previously shown to control many developmental processes, including skeletogenesis, and SOX4 was linked to osteoporosis, but how SOXC control adult bone mass remains unknown." (PMID 38580651, 2024). "MiR‐141 and SOX11 could be targets to investigate the mechanism of SANFH and other related diseases, including osteoporosis and other ossification‐related diseases." (PMID 31916393, 2020).
pancreatic cancer (4 papers, 2015 to 2022). "Some potential biomarkers, e.g. SOX11 and miR-204 which could cause cell proliferation but inhibit invasion or metastasis could be potential therapeutic targets for malignant pancreatic tumors to lighten their malignant degree." (PMID 26578390, 2015). "They indicated that lncRNA TMPO-AS1 promotes cell proliferation, migration, and invasion of pancreatic carcinoma by sponging miR-383-5p and upregulating SOX11." (PMID 36313570, 2022). "The mRNA expression of SOX11 was significantly higher in brain, breast, kidney, lung, and pancreatic cancers as well as sarcoma." (PMID 34442467, 2021). "It was found that miR-383 inhibits the progression of pancreatic carcinoma by targeting SOX11." (PMID 36313570, 2022). "Furthermore, candidate biomarkers such as SOX11 and hsa-miR-204 which could cause cell proliferation but inhibit invasion or metastasis may be of importance in understanding the molecular mechanism of pancreatic oncogenesis and could be possible therapeutic targets for malignant pancreatic tumors." (PMID 26578390, 2015).
acute myeloid leukemia (3 papers, 2020 to 2024). Acute myeloid leukemia (AML) is a group of neoplasms arising from precursor cells committed to the myeloid cell-line differentiation. "In a cohort of 50 adult acute myeloid leukemia (AML) patients, a high SOX11 expression was associated with FLT/ITD and NPM1 mutations and a shortened disease-free survival." (PMID 32029838, 2020). "MYB protein levels were previously shown to be strongly induced upon SOX11 overexpression (SOX11 OE), while celastrol has been reported to inhibit MYB activity in cancer cells (acute myeloid leukemia)." (PMID 38181013, 2024).
Arthritis (3 papers, 2021 to 2023). Inflammation of a joint. "Altogether, studies dedicated to exploring the role of SOX11 in arthritis diseases have shown that it is dysregulated during arthritis diseases progression, but more mechanistic details are still needed." (PMID 36835620, 2023). "SOX11 is elevated in patients with OA, indicating its involvement in arthritis progression." (PMID 36835620, 2023). "However, according to other studies, SOX11 is downregulated during arthritis, suggesting that it is required to prevent arthritis; therefore, further molecular details are still needed to clarify the role of SOX11 in arthritis." (PMID 36835620, 2023). "However, based on reverse-phase protein arrays conducted on the tissues of OA patients and normal chondrocytes, SOX11 was identified among the novel proteins that are downregulated during arthritis." (PMID 36835620, 2023). "Moreover, higher levels of SOX4 and SOX11 were found in the inflamed synovium of patients with arthritis." (PMID 34124371, 2021). "SOX12 appears to have no role in arthritis, however SOX11 is dysregulated and promotes arthritic progression according to some studies but supports joint maintenance and protects cartilage and bone cells according to others." (PMID 36835620, 2023). "The functionally redundant activities of Sox4, Sox11 and Sox12 in TNF-induced arthritis and the diverse range of stimuli that can potentially activate the canonical NF-κB signaling in the FLS are suggestive of a role for multiple additional co-factors besides SOXC and RELA." (PMID 35529852, 2022). "Based on the currently available data, SOX12 seems not to be involved in arthritis disease progression, while SOX11 is dysregulated and enhances arthritic progression according to some studies, but is required for joint maintenance and protects cartilage and bone cells according to other studies." (PMID 36835620, 2023). "However although it is dysregulated during OA and RA, the currently available data do not provide a conclusive overview about the role of SOX11 in arthritis." (PMID 36835620, 2023).
B-cell neoplasm (3 papers, 2011 to 2024). A group of heterogeneous lymphoid tumors generally expressing one or more B-cell antigens or representing malignant transformations of B-lymphocytes. "Our data show that the pathogenic effect of SOX11 in lymphoid neoplasias is most likely its aberrant expression associated with activating histone marks in some aggressive B-cell neoplasms." (PMID 21738649, 2011). "Pathologists should explicitly consider the blastoid variant of MCL when dealing with mature B-cell neoplasms with blastoid morphology in adults, and utilize a broad panel of ancillary studies, including FISH and SOX11." (PMID 37873796, 2023). "Recent studies have shown aberrant expression of SOX11 in various types of aggressive B-cell neoplasms." (PMID 21738649, 2011). "We observed that SOX11 expression is associated with unmethylated DNA and presence of activating histone marks (H3K9/14Ac and H3K4me3) in embryonic stem cells and some aggressive B-cell neoplasms." (PMID 21738649, 2011). "Although SOX11 does not seem to play a role in hematopoiesis, its expression has been observed in various aggressive B-cell neoplasms, suggesting that this protein plays a role in the pathogenesis of these tumors." (PMID 21738649, 2011).
ductal carcinoma in situ (3 papers, 2017 to 2024). "Here, we show that SOX11, an embryonic mammary marker that is normally silent in postnatal breast cells, is expressed in many oestrogen receptor‐negative preinvasive ductal carcinoma in situ (DCIS) lesions." (PMID 28707729, 2017).
head and neck squamous cell carcinoma (3 papers, 2024 to 2026). A squamous cell carcinoma that arises from any of the following anatomic sites: lip and oral cavity, nasal cavity, paranasal sinuses, pharynx, larynx, and salivary glands. "The transcription factor SOX11 is implicated in tumor progression across multiple types of cancers, including head and neck squamous cell carcinoma (HNSCC)." (PMID 41511366, 2026). "recently established the ability of Sox11 to regulate SDCCAG8 and to promote thereby head and neck squamous cell carcinoma (HNSCC) progression." (PMID 39039706, 2024).
invasive breast carcinoma (3 papers, 2013 to 2020). A carcinoma that infiltrates the breast parenchyma. "SOX11 expression in invasive breast cancer is associated with increased distant metastasis formation." (PMID 32909943, 2020). "Collectively, these findings support the notion that DCIS lesions that express SOX11 possess properties that make them aggressive and cause them to progress to invasive breast cancer." (PMID 28707729, 2017). "Expression of SOX11 in preinvasive breast lesions and potential sites of microinvasion in samples from DCIS cases supports a role for SOX11 in promoting in situ to invasive breast carcinoma transition." (PMID 32909943, 2020). "A recent molecular study of DCIS and early‐stage invasive breast cancers detected high levels of SOX11 expression in samples of pure DCIS and invasive tumours." (PMID 28707729, 2017). "Our findings suggest that SOX11 is a potential biomarker for DCIS lesions containing cells harbouring distinct biological features that are likely to progress to invasive breast cancer." (PMID 28707729, 2017). "Invasive lesions formed sooner and tumour growth was augmented in vivo, suggesting that SOX11 contributes to the progression of DCIS to invasive breast cancer." (PMID 28707729, 2017). "We carried out loss-of-function assays to study further the role of SOX11 in BT474 and BT549 invasive breast cancer cells, which express relatively high (BT474) and low levels (BT549) of SOX11." (PMID 23506684, 2013). "However, SOX11 is expressed in many triple negative and HER2+ invasive breast cancers." (PMID 32909943, 2020).
marginal zone lymphoma (3 papers, 2012 to 2025). A usually indolent mature B-cell lymphoma, arising from the marginal zone of lymphoid tissues. "Thus, using SOX11 as a diagnostic marker for MCL avoids misclassification of morphologically similar CD5+ marginal zone lymphomas (MZL) or CD23- chronic lymphocytic leukemia (CLL)." (PMID 22738398, 2012). "In this case, despite CD23 negativity, CD43, CD200, and LEF1 positivity support the diagnosis of CLL/SLL, whereas cyclin D1 and SOX11 negativity and LEF1 positivity exclude mantle cell and marginal zone lymphoma, respectively." (PMID 40893576, 2025). "Differential diagnosis for marginal zone B cell lymphoma mainly depends on immunohistochemistry, including at least CD20, CD10, CD5, CD23, cyclin D1, immunoglobulin D, and SOX11." (PMID 36973717, 2023).
medulloblastoma (3 papers, 2013 to 2023). A malignant, invasive embryonal neoplasm arising from the cerebellum. "Therefore, sampling HNRNPH1 and SOX11 in tumor specimens and correlating their expression with the risk of metastasis may represent a future prognostic strategy in this group of medulloblastoma." (PMID 37568705, 2023). "Importantly, differential expression of SOX genes (SOX4, SOX9, and SOX11) in pediatric brain tumors has been used as prognostic marker for disease progression and outcomes in ependymoma and medulloblastoma." (PMID 34012965, 2021). "Expression of Sox4 and Sox11 has been shown to increase in many different types of human cancers, including basal cell carcinomas (BCC) and medulloblastomas." (PMID 23658834, 2013). "TCPs may be the cells of origin of group 3 medulloblastoma and can be identified by two signature markers, HNRNPH1 and SOX11." (PMID 37568705, 2023).
schizophrenia (3 papers, 2015 to 2024). A major psychotic disorder characterized by abnormalities in the perception or expression of reality. "In order to confirm the specificity of sox11 mediated reduction in caspase-6 activity, we co-transfected caspase-6 with two other proteins, FEZ1 which was identified from the yeast-two hybrid screen and DISC1 which is a known susceptibility protein for Schizophrenia." (PMID 26505998, 2015).
small cell lung carcinoma (3 papers, 2019 to 2023). Small cell lung cancer (SCLC) is a highly aggressive malignant neoplasm, accounting for 10-15% of lung cancer cases, characterized byrapid growth, and early metastasis. "Over- expression of SOX11 was also found in small cell lung cancer, leukemia and Burkett’s lymphoma." (PMID 30922366, 2019). "We found that SOX11 showed a sensitivity similar to INSM1 and CGA, and less than SYN and CD56 in small cell lung carcinomas (SCLCs) and large cell neuroendocrine carcinomas (LCNECs)." (PMID 34996493, 2022).
triple-negative breast carcinoma (3 papers, 2020 to 2022). An invasive breast carcinoma which is negative for expression of estrogen receptor (ER), progesterone receptor (PR), and human epidermal growth factor receptor 2 (HER2). "Additionally, SOX11 could promote brain metastasis in triple-negative breast cancer (TNBC)." (PMID 36551589, 2022).
BAFopathy (2 papers, 2022). Disorder caused by mutations in the various subunits composing the BAF complex. "This analysis showed that TRIP12 is most closely related to the CSS9 (SOX11), BAFopathy (ARID1A, ARID1B, SMARCB1, SMARCA2, SMARCA4) and MRD23 (SETD5) episignatures." (PMID 36430143, 2022).
cervical cancer (2 papers, 2023 to 2025). A primary or metastatic malignant neoplasm involving the cervix. "SOX11 is a transcription factor whose expression is associated with HPV status and is downregulated in high‐grade cervical dysplasia and cervical cancer via hypermethylation of its promotor region." (PMID 39891432, 2025). "Of the three SOX genes found downregulated in Cluster 1, both SOX11 and SOX3 have been demonstrated to have oncogenic features in ovarian or cervical cancer." (PMID 37509311, 2023).
CHARGE syndrome (2 papers, 2022 to 2023). CHARGE syndrome is a multiple congenital anomaly syndrome characterized by the variable combination of multiple anomalies, mainly Coloboma; Choanal atresia/stenosis; Cranial nerve dysfunction; Characteristic ear anomalies (known as the major 4 C's). "A recent case with complex mosaic gain in the 2p25 region, which includes the SOX11 gene, was diagnosed as CHARGE syndrome, who exhibited hearing loss and inner ear deformities." (PMID 36369738, 2023).
cognitive delays (2 papers, 2022 to 2025). "The phenotype of all described patients with SOX11 variants (in the HMG domain) shows that 100 % of the individuals have developmental delay and hypoplastic fifth toenails." (PMID 33785884, 2022). "We suggest that the combination of Cogan ocular motor apraxia, hypoplastic nails of fifth toes, and developmental delay give the important diagnostic clue for a variant in the SOX11 gene (OMIM 615866, MR 27)." (PMID 33785884, 2022). "Cogan ocular apraxia in combination with developmental delay and hypoplastic nails of fifth toes might be the important diagnostic clue for recognizing patients with the variant in SOX11." (PMID 33785884, 2022).
colon adenocarcinoma (2 papers, 2022). "In contrast, SOX11 expression was significantly downregulated in colon adenocarcinoma (COAD) and rectum adenocarcinoma (READ)." (PMID 36551589, 2022).
congenital glaucoma (2 papers, 2021 to 2025). "Following normal findings using sequence analysis of 18 genes known to be associated with congenital glaucoma, we applied whole exome sequencing and identified a novel de novo heterozygous variant c.251G>T, p.(Gly84Val) in the SRY-related HMG-box gene 11 (SOX11)." (PMID 33430815, 2021). "Following normal findings with a panel diagnostic of 18 genes associated with congenital glaucoma, whole exome sequencing was performed and revealed a novel likely pathogenic heterozygous variant c.251G>T, p.(Gly84Val) in the SOX11 gene (SRY-related HMG-box gene 11)." (PMID 33430815, 2021).